DUOX1 (dual oxidase 1)
Description:
Generates hydrogen peroxide (H2O2) which is required for the activity of thyroid peroxidase/TPO and lactoperoxidase/LPO. Plays a role in thyroid hormone synthesis. Also required for lactoperoxidase-mediated antimicrobial defense at the surface of mucosa. Antimicrobial agent hypothiocyanite (OSCN-), which is produced by LPO from DUOX1-derived H2O2, promotes influenza virus inactivation by reducing viral binding to and entry into host cells. Promotes antiviral immunity by increasing airway cytokine levels, promoting innate immune cell recruitment and reducing airway epithelial cell apoptosis (By similarity). In response to bacterial stimuli, activated by ATP and promotes EGFR/ERK signaling, ADAM17 activation, and EGFR ligand shedding, leading to enhanced CXCL8/IL8 expression and secretion in airway epithelia. Synthesizes NAADP from its reduced NAADPH form which promotes Ca(2+) signaling during T cell activation. In addition to its oxidase activity, has also been shown to have peroxidase activity through its N-terminal peroxidase-like domain. However, another study showed that the isolated peroxidase-like domain does not bind heme and has no intrinsic peroxidase activity.
Synonyms: LNOX1; THOX1; NOXEF1
Tractability: Small molecule: a structure with a bound ligand is known. Antibody: UniProt places it where antibodies can reach, with high confidence; its Gene Ontology location is reachable by antibodies, with high confidence; UniProt predicts a signal peptide or a membrane-spanning region. PROTAC: a small molecule that binds it is known.
Target class: Enzyme; Oxidoreductase
Safety:
Unwanted effects reported when the protein is acted on. In parentheses: how it was acted on, where the effect was seen, and who reports it.
Altered, Amphibian metamorphosis (inhibition; source: AOP-Wiki)
Gene: Protein-coding gene on chromosome 15 (45,129,468 to 45,165,576, forward strand). Ensembl gene ENSG00000137857.
Subcellular location: Apical cell membrane
Pathways (Reactome):
Metabolism: Thyroxine biosynthesis
Gene Ontology:
Molecular function: calcium ion binding; FAD binding; heme binding; NAD(P)H oxidase H2O2-forming activity; NADPH binding; peroxidase activity; protein binding; NADP binding; protein heterodimerization activity; superoxide-generating NAD(P)H oxidase activity; oxidoreductase activity
Biological process: antiviral innate immune response; cuticle development; cytokine-mediated signaling pathway; hydrogen peroxide biosynthetic process; positive regulation of cell motility; positive regulation of defense response to bacterium; positive regulation of interleukin-8 production; positive regulation of wound healing; response to cAMP; defense response; regulation of thyroid hormone generation; superoxide anion generation; cellular response to cytokine stimulus; response to oxidative stress; response to virus; thyroid hormone generation
Cellular component: apical plasma membrane; cell leading edge; cell surface; endoplasmic reticulum; NADPH oxidase complex; plasma membrane
Genetic constraint (gnomAD): Loss-of-function variants: 132 observed, 171.33 expected, observed/expected ratio (o/e) 0.77, 90% interval 0.67 to 0.89. The upper end of that interval is the gene's LOEUF score, 0.89, which puts it in group 3 of 6, group 1 being the genes least tolerant of losing a copy. Missense variants: 1,787 observed, 2,018.5 expected, observed/expected ratio (o/e) 0.89, 90% interval 0.85 to 0.92. Synonymous variants: 784 observed, 816.39 expected, observed/expected ratio (o/e) 0.96, 90% interval 0.9 to 1.02.
Homologues: Orthologues: chimpanzee DUOX1 (99% identical), macaque DUOX1 (95% identical), dog DUOX1 (91% identical), mouse Duox1 (91% identical), rabbit DUOX1 (91% identical), pig DUOX1 (91% identical), rat Duox1 (90% identical), guinea pig DUOX1 (88% identical), tropical clawed frog duox1 (62% identical). Paralogues in human: DUOX2 (78% identical), NOX5 (13% identical), NOX3 (12% identical), CYBB (11% identical), NOX1 (11% identical), NOX4 (11% identical).
Diseases named in the same sentence as DUOX1 in open-access papers:
DUOX1 is named in the same sentence as 104 diseases in open-access papers, as found by Europe PMC text mining. Sharing a sentence is not in itself a finding about the gene and the disease. The quoted sentences say what the papers report.
lung carcinoma (16 papers, 2014 to 2026). "Theloss of DUOX1 in lung cancer cell lines was associated to decreased E-cadherin(an epithelial marker), and RNAi-mediated DUOX1 silencing induced epithelial-to-mesenchymal transition (EMT), which is closely related to metastasis." (PMID 32453337, 2020). "Here, we demonstrate a direct association between DUOX1 silencing and nEGFR function in lung cancers, and increased pathogenicity and resistance to cetuximab." (PMID 30890751, 2019). "Collectively, our findings indicate DUOX1 deficiency in lung cancers promotes dysregulated EGFR signaling and enhanced GSTP1-mediated turnover of EGFR cysteine oxidation, which result in enhanced nuclear EGFR localization and tumorigenic properties." (PMID 30890751, 2019). "DUOX1 loss has been reported in other tumor types, where it was also related to increased cellular proliferation, decreased migration in human lung cancer, and increased proliferation in human hepatocellular carcinoma." (PMID 29849884, 2018). "Here we show that loss of DUOX1 expression in a panel of lung cancer cell lines is strongly associated with loss of the epithelial marker E-cadherin." (PMID 27694834, 2016). "The present studies were conducted to address the potential association of DUOX1 silencing in lung cancer, with development of EMT and EGFR TKI resistance." (PMID 27694834, 2016). "Together, these findings demonstrate that DUOX1 silencing in lung cancer is associated with increased CSC properties." (PMID 27694834, 2016). "Interestingly, it has been shown in lung cancer cell lines that DUOX1 expression seems to be highly associated to the loss of E-cadherin." (PMID 29849884, 2018). "At this stage, it is unknown how DUOX1 silencing relates to different types of lung cancer or with specific mutations in EGFR, KRAS and so on." (PMID 27694834, 2016). "Indeed, our results demonstrate that RNAi-mediated DUOX1 silencing in lung epithelial cells and the lung cancer cell line H292 induces loss of epithelial characteristics, increases features of EMT and promotes invasive properties." (PMID 27694834, 2016). "As the process of EMT is strongly linked with increased invasive or metastatic potential of lung cancer cells, we evaluated whether DUOX1 silencing was associated with increased invasive/metastatic behavior." (PMID 27694834, 2016). "The process of EMT is strongly associated with increased characteristics of CSCs, and CD24low/CD44high sub-populations are thought to display increased CSC features, suggesting that DUOX1 silencing in lung cancer may also be associated with increased CSC characteristics." (PMID 27694834, 2016). "DUOX1 is a selective oncogene involved in tumorigenesis and cancer progression and its expression is decreased in lung cancer; however, its mechanism of action in vivo remains largely unclear." (PMID 41556052, 2026). "Introducing normal levels of DUOX1 into lung cancer cell lines increased cell migration and wound repair without affecting cell growth." (PMID 31443700, 2019). "In contrast to normal epithelial cells, EGF stimulation of lung cancer cell lines that lack DUOX1 promotes EGF-induced EGFR internalization and nuclear localization, associated with induction of EGFR-regulated genes and related tumorigenic outcomes." (PMID 30890751, 2019). "It has been found that in 50% of lung cancers NADPH oxidase DUOX1 and DUOX2 go under epigenetic silencing via hypermethylation of CpG-rich promoter regions." (PMID 31443700, 2019). "One aspect of such dysregulation is the frequent downregulation of the NADPH oxidase (NOX) family member DUOX1 in many lung cancers, largely by epigenetic mechanisms." (PMID 30890751, 2019). "In contrast, in one report, the reintroduction of functional DUOX1 into lung cancer cell lines increased cell migration and wound repair, without affecting cell growth." (PMID 29065504, 2017).
lung carcinoma (continued). "Collectively, these findings indicate that DUOX1 overexpression in lung cancer cells can indeed reverse molecular and functional features of EMT." (PMID 27694834, 2016). "Overall, these findings indicate that DUOX1 silencing in H292 lung cancer cells significantly enhances invasiveness and metastatic potential." (PMID 27694834, 2016). "Conversely, DUOX1 overexpression in lung cancer cells was able to reverse EMT features and enhance epithelial characteristics." (PMID 27694834, 2016). "Therefore, we developed a predictive nomogram that combines clinicopathological variables and DUOX1 mRNA expression to predict survival outcomes in patients with lung cancer." (PMID 41556052, 2026). "Our recent studies have suggested that DUOX1 silencing, as is observed in many lung cancers, can lead to epithelial reprogramming with features of EMT, which may also be relevant for small airway remodeling in COPD." (PMID 33301419, 2021). "Alternatively, it is possible that epigenetic mechanisms, as seen in, e.g., lung cancer, may also contribute to DUOX1 silencing in COPD." (PMID 33301419, 2021). "Previous reports showed that the low expression of dual oxidase 1 may be an indicator of poor prognosis of lung cancer, and its high expression in lung cancer cells can reverse EMT and enhance the characteristics of epithelial cells." (PMID 33063118, 2020). "In contrast, in the respiratory tract, DUOX1 is mostly expressed in the tracheal and bronchial epithelium, and DUOX1 mRNA and protein are suppressed in lung cancer as a consequence of hypermethylation in the promoter region, and this suppression is associated with poor prognosis." (PMID 31706280, 2019). "Collectively, these findings indicate DUOX1 silencing in lung cancer cells impacts on EGFR internalization and nuclear translocation in response to EGF, with corresponding consequences for EGFR-mediated cell proliferation and migration, as well as sensitivity to (antibody-based) EGFR targeting." (PMID 30890751, 2019). "Based on previous findings linking DUOX1 with redox-dependent EGFR activation, the present studies were designed to evaluate whether DUOX1 silencing in lung cancers may be responsible for altered EGFR regulation." (PMID 30890751, 2019). "Recent studies indicate that DUOX1 is suppressed in lung cancers by epigenetic silencing, although the importance of DUOX1 silencing in lung cancer development or progression is unknown." (PMID 27694834, 2016). "Indeed, DUOX1 expression status in a panel of lung cancer cell lines strongly correlated with expression of the epithelial marker E-cadherin (CDH1), suggesting that DUOX1 silencing in lung cancer is associated with loss of epithelial characteristics." (PMID 27694834, 2016). "Although our results indicate that DUOX1 silencing in lung cancer cells promotes EMT and CSC features, the question remains whether these features can also be reversed by DUOX1 overexpression." (PMID 27694834, 2016). "In summary, our findings indicate that DUOX1 silencing, a common finding in epithelial cancers, including lung cancer, may be a strong determinant of increased invasive or metastatic potential, as well as resistance to conventional anticancer therapies." (PMID 27694834, 2016). "Hence, downregulation of DUOX1 in lung cancers could lead to altered EGFR internalization pathways, and could thereby promote nuclear EGFR targeting and associated tumorigenic functions." (PMID 30890751, 2019). "Also, the observed association between DUOX1 expression and sensitivity to EGFR TKI may suggest that positive DUOX1 expression status in lung cancers may be suitable for therapeutic management with EGFR TKI, even if they express wild-type EGFR." (PMID 27694834, 2016). "Furthermore, GO enrichment analysis identified that DUOX1 may be associated with EMT, which is a key feature of aggressive and metastatic cancers, suggesting that DUOX1 may be associated with the malignant phenotype of multiple primary lung cancers." (PMID 41556052, 2026).
lung carcinoma (continued). "Another illustration is the dual oxidase 1 (DUOX1) enzyme, which contributes significantly to the generation of ROS in the airways and is frequently suppressed in human lung cancer." (PMID 37927596, 2023). "Recent evidence has indicated that DUOX1 and DUOXA1 were frequently silenced due to promoter hypermethylation in various epithelial cancers including lung cancer." (PMID 34026765, 2021). "Lung cancer also presents decreased expression of DUOX1 and DUOX2 that iscorrelated with hypermethylation of CpG-rich promoter regions of DUOX genes.Moreover, DUOXA1 and DUOXA2 weredown-regulated in lung cancer cells and lung cancer tissues." (PMID 32453337, 2020). "For example, research has shown that the promoters of DUOX1 and DUOX2 are methylated, which correlates with their downregulation at the protein level in lung cancer." (PMID 27895046, 2017). "Some reports have shown that Casp3, some claudins and DUOX1 and DUOX2 are regulated by epigenetic mechanisms during maturation of the rat brain, as well as in ovarian cancer cells and lung cancer." (PMID 27895046, 2017). "Also, while normal H292 cells showed impaired growth in the presence of erlotinib, both H292-E90 and H292-shDUOX1 cells displayed marked resistance to erlotinib up to 10 μM, indicating that DUOX1 suppression may be an important determinant of acquired erlotinib resistance in lung cancers." (PMID 27694834, 2016). "Lung cancers are frequently characterized by inappropriate activation of epidermal growth factor receptor (EGFR)-dependent signaling and epigenetic silencing of the NADPH oxidase (NOX) enzyme DUOX1, both potentially contributing to worse prognosis." (PMID 30890751, 2019). "Also, DUOX1 and DUOX2, which belong to the NAPDH oxidase family of enzymes, are methylated in human lung cancer." (PMID 27895046, 2017). "DUOX1 silencing was also found to promote EGFR TKI resistance and enhance features of CSCs, suggesting the significance of DUOX1 silencing in lung cancer as a possible indicator of lung cancers with poor prognosis or lack of responsiveness to common anticancer therapy." (PMID 27694834, 2016). "Functional enrichment analysis of DUOX1 mRNA suggests that it may be related to epithelial-mesenchymal transition and participates in the malignant biological phenotype of multiple primary lung cancers; however, it is not an independent predictor of prognosis." (PMID 41556052, 2026). "Others have suggested that DUOX1 in lung epithelia may play a role in host defence, and silencing of DUOX1, DUOX2 and their respective maturation factors has been demonstrated in lung cancer cells." (PMID 24410844, 2014). "Similar reversal of EMT features were observed after overexpression of DUOX1, but not DUOXA1, in the metastatic lung cancer cell line NCI-H187 in which DUOX1 is also silenced." (PMID 27694834, 2016).
thyroid cancer (11 papers, 2013 to 2025). "Ionizing radiation, a well-known risk factor for thyroid cancer, was recently shown to exert its effects in part through DUOX1-derived H2O2." (PMID 30728883, 2019). "Notably, DUOX1 has been shown to promote persistent DNA damage in human thyrocytes following irradiation, which is recognized as a significant risk factor for thyroid cancer." (PMID 40620232, 2025). "The role of DUOX1 and 2 has been extensively studied in the context of thyroid cancer differentiation and progression, however, and to our knowledge this is the first study that describes their role in DKD." (PMID 34680477, 2021). "In thyroid cancer, DUOX1 is upregulated upon radiation, and DUOX1-dependent H2O2 production promotes persistent DNA damage and genome instability, which might contribute to cancer development." (PMID 31706280, 2019). "Overexpression of DUOX1 and DUOX2 in thyroid cancers was also reported, however, the results are inconsistent." (PMID 30558263, 2018). "DUOX1 and DUOX2, formerly known as thyroid oxidases, were specifically expressed in thyroid cancers (THCA)." (PMID 28582771, 2017). "Gene expression of NOX4, DUOX1 and DUOX2 was not increased in kidney and thyroid cancers with high-level apoptosis and energy metabolism (data not shown), implying some other genes acting as the indicators of oxidative stress." (PMID 28582771, 2017).
hepatocellular carcinoma (9 papers, 2016 to 2023). A malignant tumor that arises from hepatocytes. "In addition, DUOX1 has been identified as a risk factor for the prognosis of hepatocellular carcinoma patients after surgery." (PMID 29065504, 2017). "In hepatocellular carcinoma, DUOX1 expression has been found to correlate with improved overall survival." (PMID 37759986, 2023). "Available data suggest that DUOX1 is also often suppressed in hepatocellular carcinoma, a carcinoma of epithelial origin similar to PDAC." (PMID 37759986, 2023). "Epigenetic silencing of DUOX1 expression was reported in lung and hepatocellular carcinomas suggesting a possible tumor suppressing role for DUOX1." (PMID 31083324, 2019). "In our study, NOX1/4/5 and DUOX1/2 expression was higher in hepatocellular carcinoma tissues than in control normal liver tissues." (PMID 28894215, 2017). "In addition, the DUOX1 mRNA expression level in hepatocellular carcinoma tissues is lower than that in non-cancerous tissues." (PMID 29065504, 2017). "DUOX1 promoter methylation was detected in primaryhepatocellular carcinoma (HCC), but not in non-tumor tissues." (PMID 32453337, 2020). "Moreover, in 2014, Ling and collaborators found that DUOX1 expression is also frequently decreased in most liver cancer cell lines and primary hepatocellular carcinoma (HCC) tissues compared to its expression in non-tumor tissues." (PMID 36290761, 2022).